CYLD (CYLD lysine 63 deubiquitinase)
Diseases named in the same sentence as CYLD in open-access papers (continued):
Sharing a sentence is not in itself a finding about the gene and the disease.
tumor (continued). "Therefore, it is possible that another tumor suppressor function for CYLD may be to activate the RIPK1 death-signaling response, and antagonizing this death pathway by deleting or otherwise inhibiting CYLD would be expected to provide a survival advantage to tumors." (PMID 32024820, 2020). "With the regulation of the tumor microenvironment, more genes were upregulated with over two-fold differences in both HK1 and C17 xenografts after CYLD knockout, including BCL2A1, CXCL1, BIRC3, SERPINB2, total VEGF, TNFA, and VEGFA." (PMID 32708712, 2020). "However, because CYLD is also involved in the NF-kB pathway, which mediates inflammation and tumor growth, the effects of CYLD downregulation may not only be associated with necroptosis." (PMID 31122251, 2019). "The gene profiles indicated that YM155 down-regulated ID1 and BIRC5 which are tumour promoters, and upregulated CYLD and FOXO1 which are tumour suppressors." (PMID 28582447, 2017). "mRNA and protein analyses confirmed that YM155 downregulated the tumour promoters BIRC5 and ID1 and upregulated the tumour suppressors FOXO1 and CYLD." (PMID 28582447, 2017). "Therefore, it appears that CYLD may suppress tumour development by different mechanisms acting either in a cell intrinsic manner in premalignant epithelial cells or by regulating the tumour microenvironment by acting in myeloid cells." (PMID 27561390, 2016). "It was further noted that the tumor number and size in CYLD−/− and CYLD+/− mice did grow over time after the initial DMBA/TPA insult, which is also reminiscent of the tumor characteristics reported in patients with the syndrome." (PMID 31093340, 2016). "To determine whether inherited, CYLD‐defective tumours express MYB–NFIB fusion transcripts, we adopted a validated RT–PCR strategy for exploring the presence of such transcripts in a collection of 13 snap‐frozen and 10 FFPE tumours derived from patients with BSS with confirmed CYLD mutations." (PMID 26969893, 2016). "Our data highlights a novel interacting partner of CYLD, MIB2, that influences Notch signalling and furthermore the potential therapeutic utility of γ-secretase inhibition in CYLD defective tumours." (PMID 25565632, 2014). "Five tumor suppressors or suppressor candidates including NRIP3, CYLD, CD9, ATF3 and OXTR were strongly induced by TSA alone." (PMID 18301774, 2008). "It promotes tumor cell survival, proliferation, and invasion via EGFR-induced NF-κB activation, while its scaffolding and protease activities regulate key signaling pathways, including the inactivation of NF-κB pathway inhibitors, specifically A20 and CYLD." (PMID 40338274, 2025). "Given of CYLD’s tumor-suppressive role, it is not surprising to observe its involvement in the pathogenesis of brain tumors." (PMID 39945824, 2025). "However, CYLD was also reported to serve as a tumor-suppressive DUB by negatively modulating the oncogenic activation of NF-κB, revealing its dual role in tumor progression." (PMID 38715050, 2024). "In addition, our findings suggest that inhibition of MALT1-mediated CYLD cleavage, through other BCR signalosome inhibitors such as ibrutinib and sotrastaurin, contributes to the anti-tumor effects of these drugs." (PMID 36922488, 2023). "Taken together, studying the DUB and non-DUB functions of CYLD has identified mechanisms that support its role as a tumour suppressor, as well as its roles in regulating diverse cellular processes." (PMID 37387450, 2023). "To further evaluate the prediction power of candidate biomarkers that have greater likelihoods of becoming clinically useful markers for NPC diagnosis and for monitoring tumor progression, we built multiple logistic regression models considering the expression of CDH4, STAT4, CYLD and LMP1." (PMID 37393410, 2023). "Finally, we demonstrated that tumor-specific deletion of SPATA2 and CYLD enhances anti-PD-1 response in vivo." (PMID 36531014, 2022).
tumor (continued). "To determine whether CYLD exerts a similar effect on tumor-intrinsic chemokine production as SPATA2, we transiently knocked down CYLD by RNAi and measured CXCL9, CXCL10, and CXCL11 secretion." (PMID 36531014, 2022). "Therefore, the relationship of CYLD and EBV replication was analyzed in NPC tissues and a tumor tissue microarray." (PMID 33654169, 2021). "CYLD is the negative modulator of PI3K/AKT/NF-κB axis and is also implicated in regulation of tumor cell apoptosis." (PMID 34099061, 2021). "This study revealed another tumor-suppressive function of CYLD in inducing cell death, independent of extrinsic death receptor signaling." (PMID 33919439, 2021). "When considering smoking history, CYLD mRNA expression was significantly lower in tumor tissues from smokers than from non-smokers." (PMID 34326699, 2021). "Restoring CYLD prevents EBV induced viral replication and tumor growth." (PMID 33654169, 2021). "OTULIN/CYLD can interact with LUBAC (linear ubiquitin chain assembly complex) through the PUB (PNGase/UBA or UBX) domain of HOIP (a catalytic subunit of LUBAC), thereby inhibiting the NF-κB pathway and exerting anti-tumor effects." (PMID 33498168, 2021). "In this study, the impact of CYLD on regulating the NF-kB signaling pathway and its contribution to NPC development was studied using in vitro and in vivo functional assays, together with single cell RNA sequencing to understand the NPC tumor microenvironment." (PMID 32708712, 2020). "In both HK1 and C17, CYLD knockout enhances in vivo tumor growth compared to the non-targeted control, while CYLD overexpression suppresses tumor growth compared to vector-alone (VA)." (PMID 32708712, 2020). "In conclusion, the findings that CYLD regulates three cancer hallmarks and mediates stromal cell infiltration in TME in NPC indicate it plays a major tumor-suppressive role in NPC tumorigenesis and metastasis by negatively regulating the NF-kB signaling pathway." (PMID 32708712, 2020). "Additionally, CYLD was able to inhibit fibroblast and endothelial stromal cell infiltration into the NPC tumor microenvironment." (PMID 32708712, 2020). "Three tumor suppresser genes, including CYLD, ATM, and TSPYL2, showed a negative correlation with UBE2C in several cancers with a similar moderate to strong negative correlation for them in the following cancers: LUSC, READ, UCEC, OV, and UCS." (PMID 31067633, 2019). "This analysis revealed that the metastatic Tg(Grm1) Cyld−/− cells show a reduced doubling time in comparison to Cyld-expressing cells, whereas the proliferative potential from primary tumor cells with or without CYLD expression was comparable." (PMID 31591386, 2019). "Therefore, it seems that CYLD, like other well-known tumor suppressor proteins such as Ink4a, Arf and PTEN, acts as a tumor suppressor in a variety of malignancies." (PMID 30631004, 2019). "Most studies so far attributed the tumour suppressing properties of CYLD to its function as negative regulator of NF-κB, MAPK and Wnt signalling." (PMID 27561390, 2016). "Strikingly, none of the inherited CYLD‐defective (n = 23) tumours expressed MYB–NFIB fusion transcripts." (PMID 26969893, 2016). "The study demonstrated that as early as second round of DSS treatment, the CYLD−/− mice developed multiple measurable broad-based adenocarcinomas (i.e. flattened, or called sessile) in the colonic epithelium, as compared to almost no tumor in the CYLD+/+ mice." (PMID 31093340, 2016). "However, MYB expression was increased in the majority of tumours (69%) and global gene expression analysis revealed that well‐established MYB target genes were up‐regulated in CYLD‐defective tumours." (PMID 26969893, 2016). "Furthermore, western blotting analysis revealed that the expression of CYLD, TAX1BP1 and OTUD7B dramatically decreased in the miR-500–overexpressing tumours but increased in miR-500–silenced tumours." (PMID 25595906, 2015).
tumor (continued). "We cannot exclude that nuclear expression of CYLD might be an early event in HCC development, which disappears upon tumor progression, or CYLD simply changes its subcellular location." (PMID 25329885, 2014). "Here we show for the first time that lacking nuclear expression of the deubiquitinase CYLD in HCC tumor tissues strongly correlates with poor outcome of patients." (PMID 25329885, 2014). "CYLD was previously identified as an important regulator not only in tumor development but also in adaptive immune response." (PMID 18664270, 2008). "We suggested that other biallelic inactivation of FAT1, TRIP12 and CYLD (as well as PTEN) could occur through promoter methylation of these four genes in the tumours showing only monoallelic inactivation (only LOH without somatic mutation or only somatic mutation without LOH)." (PMID 29416628, 2018). "However, our in vivo genetic studies showing that double FADD/RIPK3 deficiency did not sensitize mice to AOM-induced colon tumorigenesis provided evidence that regulation of death receptor-induced programmed cell death is not critical for the tumour suppressing role of CYLD." (PMID 27561390, 2016). "Although there are studies describing different signaling pathways regulated by CYLD during infection, inflammation and neoplasia, it is not known whether and how positive transcription regulation of CYLD on the promoter level is orchestrated in non transformed cells." (PMID 21573132, 2011). "However, despite recent studies demonstrating the role of CYLD in regulating T cell receptor signaling and tumor cell proliferation in vivo, the biological role of CYLD especially its negative role in inflammation in vivo still remains unknown." (PMID 17925880, 2007). "In this CYLD-negative CDX models, gefitinib treatment significantly suppressed tumor growth during administration period." (PMID 36376983, 2022). "An inverse correlation of CYLD protein expression with mitotic activity (as assessed by the MIB1-index), but not with tumor stage, has been reported by others in human HCC." (PMID 25329885, 2014). "Furthermore, CYLD phosphorylation down-regulation by BTK inhibitors induces cell apoptosis and tumor growth inhibition in non-GCB-DLBCL, especially in the rituximab-resistant relapsed/refractory cases." (PMID 34454635, 2021). "The synchronously change of CYLD phosphorylation and BTK phosphorylation suggested that CYLD phosphorylation should be regulated through inhibition of BTK phosphorylation, which might regulate tumor cell death in non-GCB-DLBCL." (PMID 33827598, 2021).
cancer (122 papers, 2010 to 2026). A tumor composed of atypical neoplastic, often pleomorphic cells that invade other tissues. "Due to the clinical course and family history of the patient, a molecular study using a multigene panel for cancer predisposition genes including the CYLD gene, was performed." (PMID 39430072, 2024). "Loss of CYLD function can result in uncontrolled cellular proliferation, which is a hallmark of cancer." (PMID 39430072, 2024). "The homozygous loss of CYLD resulted in quicker cancer development and progression as well as increased neoangiogenesis." (PMID 38672652, 2024). "Beyond CCS, loss of CYLD function is increasingly recognised to play a role in a range of human cancers." (PMID 37387450, 2023). "Dysregulation or dysfunction of CYLD has indeed been implicated in a number of human diseases, including, but not limited to, cancer, infectious disease and multiple neurodegenerative disorders." (PMID 37387450, 2023). "In this regard, it is likely that s CYLD mutation or deficiency in some cancers decreases its deubiquitination activity against K63-linked or M1-linked Ub chains, leading to insufficient activation of RIPK1-mediated cell death." (PMID 36171264, 2022). "Accordingly, genetic studies have shown that CYLD is frequently inactivated by somatic mutations in many cancers, including hepatocellular carcinoma, multiple myeloma, and head and neck cancer." (PMID 36171264, 2022). "Studies have shown that alterations in the CYLD gene are closely related to HPV-associated cancers, it activates NF-κB and is implicated in invasion and metastasis." (PMID 33498168, 2021). "These attributes are consistent with a phenotypic transition from a benign behavior to an invasive one, which can be triggered by the loss of CYLD protein function or expression, most likely at a late stage of cancer progression." (PMID 32722292, 2020). "Although there are a number of studies associated with CYLD function in different cancers, its function has yet to be more extensively explored in NPC." (PMID 32708712, 2020). "In clinical practice, it has been reported that loss of CYLD expression correlates with progression and prognosis in several types of cancer." (PMID 33031450, 2020). "Since then, both depletion and mutation of CYLD have been associated with development and progression of a variety of tumors such as cancer of the breast, colon and lung." (PMID 31591386, 2019). "On the other hand, little is known about the functional importance of CYLD mutations in NPC or other cancers." (PMID 28098136, 2017). "Currently, the role of CYLD mutations in head and neck carcinogenesis and other cancers is poorly defined." (PMID 31093340, 2016). "CYLD removes lysine (K-63)-linked polyubiquitin chains from proteins regulating signaling pathways involved in cancer development and progression." (PMID 25329885, 2014). "Given that literature reporting that ferroptosis could inhibit cancer progression and the Hippo pathway was closely associated with ferroptosis, we speculated whether CYLD acted as an inhibitory effect on PCa through ferroptosis." (PMID 38246916, 2024). "Moreover, cancer-related mutations alter CYLD structure and which disturb its binding capacity to K63 ubiquitin molecule." (PMID 36202787, 2022). "Furthermore, CYLD-deficient cancer cells are resistant to cell death induced by anticancer compounds." (PMID 33919439, 2021). "We propose that the simultaneous disruption of CYLD and selective autophagy by Cd feeds a vicious cycle that further amplifies K63-linked ubiquitination and downstream activation of the NF-κB pathway, processes that support cancer progression." (PMID 34065348, 2021). "In addition to these overlapping histopathologic changes, we further note that these carcinomas from both sites show consistent CYLD mutations, HPV positivity, low TMB, low frequency of PIK3CA mutations, and likely propensity to metastasize to the liver." (PMID 32892208, 2021).
cancer (continued). "Thus, the up-regulation of CYLD activity is associated with neurodegenerative diseases, whereas the down-regulation of CYLD causes cancers." (PMID 32403254, 2020). "This may imply that CYLD loss, together with a strong cancer inducing agent or DNA mutagen, can turn normal cells to tumors with the potential to further transform into malignancies." (PMID 31093340, 2016). "An additional 15 cancer types harbor somatic CYLD mutations at ~1-3 % rates." (PMID 31093340, 2016). "Indeed, CYLD is located in chromosome 16q and its expression is reduced in 16q-loss cancer groups (A, B1, and D), thus suggesting that its decreased function could cooperate in the hyperactivation of conventional or non-conventional Wnt pathways." (PMID 33808143, 2021). "Since previous studies showed that loss of CYLD function leads to the suppression of apoptosis by NF-κB hyperactivation in malignant tumors, we next sought to determine whether the suppression of apoptosis was involved in cisplatin resistance caused by CYLD down-regulation in SAS cells." (PMID 31635163, 2019). "Unlike the impact of A20 and Cezanne, the CYLD p.E747K and c.2242+169 variants in the exon 15 had protective effects for B-ALL in this study, although CYLD inactivation is related to the pathogenesis of T-lymphoblastic leukemia and cancers." (PMID 40731796, 2025). "The results showed that CYLD knockdown in DU145 cells decreased the sensitivity of cancer cells to ferroptosis, while CYLD overexpression in PC-3 cells, 22RV1 and DU145 cells increased the sensitivity of cancer cells to ferroptosis." (PMID 38246916, 2024). "Our novel Rosa26-Cyld-tdTomato mice provide a valuable tool for exploring CYLD’s function across various cell types, potentially advancing our understanding of inflammatory disorders and cancer." (PMID 39302418, 2024). "Another study demonstrated that NF-κB, a transcription factor known for its involvement in cancer development and progression, is regulated by CYLD." (PMID 38672652, 2024). "Previously, we have identified that CYLD inhibited cell cycle G1 to S phase transition by deubiquitinating p18, then negatively regulating cancer-cell proliferation." (PMID 38287022, 2024). "CYLD, a novel deubiquitinating enzyme, always acts as a tumor suppressor gene in the development and progression of many cancers." (PMID 38246916, 2024). "Though CYLD is always considered to play as an inhibitory role in most cancer types, the type of inhibitory function is highly specific to each cancer type." (PMID 38246916, 2024). "CYLD alterations have been detected in several types of human cancers, including colon cancer, hepatocellular carcinomas, melanoma, and head and neck cancers." (PMID 37393410, 2023). "CYLD lysine 63 deubiquitinase (CYLD) is a ubiquitin hydrolase with important roles in immunity and cancer." (PMID 37387450, 2023). "Despite that in most cases the molecular basis of CYLD involvement remains elusive, in some types of cancer a relevant molecular mechanism has been identified." (PMID 37894364, 2023). "In contrast to the previous report showing the gefitinib resistance caused by low-CYLD expression in NSCLC, it was the first repot that EGFR-TKIs were indeed effective for CYLD-negative cancer patients." (PMID 36376983, 2022). "STAT3 is not only a downstream target of IL-6, but, along with miR-181b-1, miR-21, PTEN and CYLD, lysine 63 deubiquitinase is part of the positive feedback loop regulating the epigenetic switch linking inflammation to cancer." (PMID 36010971, 2022). "Subsequent researches reported that CYLD targeted and regulated a variety of signaling pathways, and revealed that loss of CYLD function might play various and pivotal roles in a variety of diseases caused by abnormal intracellular signaling, especially in malignant tumors." (PMID 36376983, 2022). "Consistent with in vitro observations, reduced levels of CYLD expression have been reported in various human cancer tissues." (PMID 36171264, 2022).